RNU105C (RNA, U105C small nucleolar)
Synonyms: E1-5; E1-6; U105C
Gene: Small nucleolar RNA gene on chromosome 8 (54,330,687 to 54,330,895, forward strand). Ensembl gene ENSG00000199212.
Gene Ontology:
Biological process: RNA processing
Cellular component: nucleolus
Homologues: Orthologues: chimpanzee SNORA73 (98% identical), macaque SNORA73 (88% identical), rabbit SNORA73 (78% identical), rabbit SNORA73 (76% identical), guinea pig SNORA73 (73% identical), rabbit SNORA73 (67% identical). Paralogues in human: SNORA73B (83% identical), SNORA73A (81% identical), SNORA73 (75% identical), SNORA73 (74% identical), RNU105B (73% identical), SNORA73 (67% identical), SNORA73 (35% identical).
Diseases named in the same sentence as RNU105C in open-access papers:
RNU105C is named in the same sentence as 3 diseases in open-access papers, as found by Europe PMC text mining. Sharing a sentence is not in itself a finding about the gene and the disease.
RNU105C shares sentences with these, for which no sentence is quoted: Fibroadenoma (1 paper); invasive lobular carcinoma (1); tumor (1).